TLR2 (toll like receptor 2)
Diseases named in the same sentence as TLR2 in open-access papers (continued):
Sharing a sentence is not in itself a finding about the gene and the disease.
prion disease (9 papers, 2012 to 2025). A transmissible disease that is caused by a protein that is able to induce abnormal folding of normal cellular proteins, leading to characteristic spongiform brain changes, which are associated with neuronal loss without an inflammatory response. "(in vivo) Prion disease model: scrapie infection in mice (WT, TLR2 deficient, C3aR deficient, and C5aR deficient)." (PMID 34408631, 2021). "Considering this crosstalk and that Tlr2, C5ar1, and C5a were increased in the brain, we hypothesized that loss of either of the receptors would influence gene expression of an overlapping subset of proinflammatory markers during prion disease." (PMID 30596651, 2018). "TLR2 and TLR4 signaling are important for sensing damage-associated molecular patterns (DAMPs) and has been shown to be implicated in prion disease, as knocking out either of these receptors in mice accelerates disease." (PMID 40532025, 2025). "While the role of TLR2 in prion diseases is not fully understood, beneficial effects have been proposed: survival time is reduced in mice that do not express TLR2 following intracerebral inoculation with scrapie." (PMID 35408945, 2022). "To investigate the role of some of these proteins in prion disease of the CNS, we infected mice deficient in DAMP receptor genes Tlr2, C3ar1, and C5ar1 with 22L scrapie." (PMID 30596651, 2018). "In terms of prion disease this suggests the considerable increase in expression of TLR2 observed at clinical stages of prion disease could be indicative of the accumulation of microglia that are not in an activation state that is optimal for phagocytosis." (PMID 22363497, 2012). "Investigation into whether TLR2 signaling is indeed important in prion disease pathology, and the identification of signaling pathways important in microglial activation independent of MyD88, warrants further investigation." (PMID 22363497, 2012). "Our data revealed that the TLR2 and TLR9 subfamilies exhibited increased expression during the pathogenesis of prion disease." (PMID 38698886, 2024). "The possible mechanistic links of the remaining genes in the SCC (TLR2, NCF1, PTPN6 and B2M) to prion disease are still open." (PMID 23068602, 2012). "Interestingly, depletion of any of the DAMP receptor genes Tlr2, C3ar1, and C5ar1 in a prion mouse model only led to a slightly increased survival in the Tlr2-model, while C3ar1, and C5ar1 did not influence prion disease course." (PMID 36230910, 2022).
schizophrenia (9 papers, 2015 to 2026). A major psychotic disorder characterized by abnormalities in the perception or expression of reality. "Studies also show that TLR polymorphisms are associated with schizophrenia, such as tlr2 polymorphism in the Tunisian population." (PMID 37627253, 2023). "Missense polymorphisms (rs5743708 and rs121917864) located in the third exon of tlr2 gene were considered to increase the risk and susceptibility to schizophrenia." (PMID 37627253, 2023). "In the present study, we first demonstrated that a deficiency of the TLR-2 gene caused schizophrenia-like behavioral, histological, and biochemical characteristics in mice." (PMID 25687169, 2015). "On the other hand, the TLR-2 gene is located at chromosome 4q32, a region that has been shown to be linked to positive schizophrenia-interpersonal sensitivity in schizophrenia patients." (PMID 25687169, 2015). "Conclusively, we showed in this study that the deletion of the TLR-2 gene in mice causes the typical behavioral, histological, and pathophysiological characteristics observed in schizophrenia patients." (PMID 25687169, 2015). "A significant association between TLR-2 gene polymorphisms and clinical cognitive symptoms has also been observed in schizophrenia patients." (PMID 25687169, 2015). "This indicates the broad (multiethnic) implications of TLR2 polymorphism in schizophrenia." (PMID 37627253, 2023). "In another study, two SNPs, rs3804099 and rs3804100 (of unknown function), located in the third exon of tlr2 gene, were reported to be significantly associated with poor concentration in the Korean schizophrenia population." (PMID 37627253, 2023). "However, it should be pointed out that this study is limited to provide the direct evidence which TLR-2 is associated with schizophrenia." (PMID 25687169, 2015). "Ventricle enlargement, a hallmark of schizophrenia, was also observed in TLR-2 KO mouse brains." (PMID 25687169, 2015). "Thus, our data suggest that the dysregulation of the innate immune system by a TLR-2 deficiency may contribute to the development and/or pathophysiology of schizophrenia-like behaviors via Akt-GSK-3α/β signaling." (PMID 25687169, 2015). "On the contrary, decreased cognitive performance in patients with schizophrenia was observed with higher TLR2 activity (whole blood-stimulated) and elevated IL-6 plasma." (PMID 37627253, 2023). "Here, we demonstrated that toll-like receptor (TLR)-2, a family of pattern-recognition receptors, is involved in the pathogenesis of schizophrenia-like symptoms." (PMID 25687169, 2015). "To examine whether TLR-2 KO mice would show the morphological characteristics of schizophrenia including ventricle enlargement, we performed histochemical and magnetic resonance imaging (MRI) studies." (PMID 25687169, 2015). "Although the critical issue of whether prenatal immune activation could induce schizophrenia-like symptoms should be investigated, the present study suggests that an alteration of TLR-2 functions in the CNS may contribute to schizophrenia etiology." (PMID 25687169, 2015). "In contrast, whole blood stimulation studies in schizophrenia showed elevated concentrations of IL-6, TNF-α, and IL-1β post-TLR2 stimulation, and increased IL-1β alone post-TLR4 and 8 stimulation." (PMID 37627253, 2023). "Behavioral alterations in TLR-2 KO mice were relevant to the symptoms of schizophrenia, such as the positive, negative, and cognitive symptoms." (PMID 25687169, 2015).
septic arthritis (9 papers, 2017 to 2025). "Our results suggest that Lpp have limited impact on the development of hematogenous septic arthritis in WT mice, whereas TLR2 deficiency gives more severe clinical septic arthritis, which is somehow contradictory to our previous findings." (PMID 32404866, 2020). "The post-infectious arthritis is more likely to evolve into chronic SpA in HLA-B27+ individuals, a progression possibly related to TLR2 polymorphisms." (PMID 28824645, 2017). "However, since Lpp is predominant bone erosion inducer in septic arthritis and the bone erosive effect of Lpp is strictly dependent on TLR26, bone destruction tended to be less pronounced in the TLR2 deficient mice compared to wild-type mice despite displaying more clinical septic arthritis." (PMID 32404866, 2020). "In septic arthritis, TLR2 was found to play a pro-inflammatory and catabolic role mediated by the NF-κB pathway." (PMID 41170422, 2025). "For instance, certain TLR2 agonists or inhibitors have demonstrated the potential to modulate inflammatory responses through STAT3/SOCS3 signaling in a murine model of septic arthritis." (PMID 41170422, 2025). "Here, we aim to investigate the importance of S. aureus Lpp and TLR2 in a hematogenous septic arthritis model, which is the most common route of infection in humans." (PMID 32404866, 2020). "In this study, we investigated the effect of staphylococcal Lpp and TLR2 in a murine model of S. aureus-induced hematogenous septic arthritis." (PMID 32404866, 2020). "In the present study, we investigated the role of staphylococcal Lpp as well as TLR2 in our well-established hematogenous mouse model of S. aureus-induced septic arthritis." (PMID 32404866, 2020). "Considering that IL-33 interferes with TLR signaling, it is reasonable to suppose that in ST2−/− mice with septic arthritis, TLR2 signaling will be boosted allowing neutrophils and macrophages to produce larger amounts of NO via iNOS to eliminate the bacteria." (PMID 29867945, 2018). "Indeed, in our well-established murine model of hematogenous septic arthritis, intravenous inoculation with the S. aureus Newman parental strain resulted in higher bacterial persistence in kidneys of both C57BL/6 wild-type and TLR2 deficient mice." (PMID 36262324, 2022). "Notably, the worst outcome was observed in mice lacking TLR2 and inoculated with the S. aureus parental strain, strongly indicating the protective role of TLR2 in hematogenous spread of S. aureus-induced septic arthritis." (PMID 36262324, 2022). "In the hematogenous septic arthritis model, expression of Lpp in S. aureus increased mortality, weight loss and cytokine production, and decreased bacterial clearance independent of TLR2, indicating the important role of Lpp in bacterial fitness and virulence." (PMID 36262324, 2022). "Indeed, S. aureus lipoproteins potently target macrophage TLR2 to induce chemokines secretion and to either trigger septic arthritis (if lipoproteins were administered alone) or to strengthen the clearance of bacteria in the case of infection." (PMID 33396944, 2020). "In this section, the specific functions of TLR2 and FPR receptors will be discussed in depth in regard to S. aureus septic arthritis and their latest research progress, elucidating their key roles in pathogen recognition and host defense." (PMID 41170422, 2025). "In a mouse model of S. aureus septic arthritis, Lpps gave rise to pronounced arthritogenic effects in both NMRI and C57BL/6 wild-type mouse strains, whereas TLR2 deficient mice displayed no signs at all following intra-articular knee joint challenge with the purified Lpl1(+sp)." (PMID 36262324, 2022).
acute respiratory distress syndrome (8 papers, 2016 to 2025). Progressive and life-threatening pulmonary distress in the absence of an underlying pulmonary condition, usually following major trauma or surgery. "In summary, our study confirmed that SYQP induced bidirectional immunity and ameliorated LPS-induced acute respiratory distress syndrome in mice through TLR2/TLR4-NF-κB, NLRP3/caspase and JAK/STAT signaling pathways, which provided a theoretical basis for further use of SYQP." (PMID 35370633, 2022). "It is therefore possible that the excess lung damage was subsequent to primed neutrophil retention rather than to TLR2 overexpression, as described in patients with acute respiratory distress syndrome (ARDS)." (PMID 27391952, 2016).
bacterial meningitis (8 papers, 2011 to 2026). Inflammation of the membranes surrounding the brain and spinal cord due to a bacterial infection. "In its role as a sensor for Gram-positive bacteria, TLR2 is also implicated in the pathogenesis of acute CNS infections such as bacterial meningitis." (PMID 39590870, 2024). "Also, in bacterial meningitis provoked by Streptococcus (which bears NA), TLR2 activation mediates neuronal death and microglial apoptosis." (PMID 31791382, 2019). "Further, in adult mice, hyaluronan blocks oligodendrocyte progenitor maturation and remyelination through TLR2 pathway; Intrathecal administration of Pam3CSK4 induces the pathophysiological hallmarks of bacterial meningitis and neuronal damage in a TLR2-dependent fashion in adult rats." (PMID 21573120, 2011). "During bacterial meningitis, BCW interacts with TLR2/1 to initiate inflammation and neuronal damage." (PMID 37052506, 2023). "Among TLRs, TLR2, TLR4, TLR9 are involved in the pathogenesis of bacterial meningitis." (PMID 33808027, 2021).
brain injury (8 papers, 2011 to 2022). Acute and chronic (see also brain INJURIES, CHRONIC) injuries to the brain, including the cerebral hemispheres, CEREBELLUM, and brain STEM. "We have recently found that repeated stimulation of the TLR-2 receptor during early neonatal development by administration of the TLR-2 agonist Pam3CSK4 results in brain injury and this effect is blocked in TLR-2 deficient mice." (PMID 21569241, 2011). "Although the proportion of resident macrophage MGs was lower than control after brain injury, they remained active phagocytic function through enhanced TLR2 expression in both mild and severe brain injury." (PMID 32903800, 2020). "Since the role of TLR2 and 4 after traumatic brain injury (TBI) is still unclear, we examined the outcome and the expression of pro-inflammatory mediators after experimental TBI in Tlr2/4−/− and wild-type (WT) mice." (PMID 28912751, 2017). "Inflammation is one of the hallmarks of hypoxic ischemic encephalopathy and experimental studies suggest that the absence of either TLR2 or TLR4 is associated with protection against ischemic brain injury." (PMID 31369614, 2019). "Our narrative review suggests that TLR2 and TLR4 are known to have a larger role in the pathological progression of ischemic brain injury than other TLRs." (PMID 35510663, 2022).
cardiomyopathy (8 papers, 2012 to 2025). A disease of the heart muscle or myocardium proper. "In this study, utilizing LCZ696 and TLR2 knockout mice, we investigated the effect of LCZ696 and TLR2 deficiency on DOX-induced mouse cardiomyopathy." (PMID 33928085, 2021). "Furthermore, the underlying mechanisms involved in DOX-induced cardiomyopathy were revealed that DOX stimulated the formation of the TLR2-MyD88 complex, which activated the NF-κB pathway, leading to cardiac cell inflammation and fibrosis." (PMID 33928085, 2021). "Blocking TLR2 activity reduces mortality, attenuates cardiac dysfunction, and inhibits myocardial fibrosis in doxorubicin-induced cardiomyopathy." (PMID 40064787, 2025). "In line, TLR2 KO mice showed better cardiac function and survival in a doxorubicin-induced cardiomyopathy model compared to Wt mice in another study." (PMID 39201339, 2024). "Next, we examined whether inflammation mediated the disparate responses of TLR2 or TLR4 inhibition in Dox-induced cardiomyopathy." (PMID 22808256, 2012). "Toll-like receptors (TLRs), particularly TLR2 and TLR4, play crucial roles in doxorubicin-induced cardiotoxicity and cardiomyopathy." (PMID 40064787, 2025). "The Co-IP assay results showed that DOX significantly increased the TLR2-MyD88 interaction in 15 min, which indicated the potential mechanism of TLR2-mediated DOX-related cardiomyopathy." (PMID 33928085, 2021). "The objective of this study was to evaluate the therapeutic effect of TLR2 and TLR4 blockade on already established Dox induced cardiomyopathy." (PMID 22808256, 2012).
Chagas disease (8 papers, 2010 to 2021). A parasitic infection caused by Trypanosoma cruzi. "TLRs are involved in both protection against and the pathology of Chagas disease, and among these receptors, it is estimated that TLR2, TLR4, and TLR9 are the most important." (PMID 25371910, 2014). "During Trypanosoma cruzi infection, the causative agent of Chagas disease, it was shown in a mouse model of infection that MAL deficiency is associated to exacerbated inflammation, similarly to TLR-2 deficient mice, leading to decreased parasitemia and delayed mortality." (PMID 33072109, 2020). "In parallel, T. cruzi-glycosylphosphatidylinositol membrane anchor is recognized by both, TLR-2 and TLR-9, and exert a role in the prognosis of asymptomatic and cardiac clinical forms of Chagas disease." (PMID 34113663, 2021). "Recently, we reported that TLR2, TLR4 and TLR9 are differentially modulated in injured livers from BALB/c and C57BL/6 (B6) mice during Trypanosoma cruzi infection." (PMID 21072226, 2010). "Concerning Trypanosoma cruzi, the agent of Chagas disease, we have previously characterized glycosylphosphatidylinositol (GPI) anchored mucin-like glycoproteins (tGPI-mucin) and unmethylated CpG DNA sequences as TLR2 and TLR9 agonists, respectively." (PMID 23650544, 2013).
Chlamydia infection (8 papers, 2011 to 2023). "We compared alveolar macrophages (AM) prepared from the lungs of control and TLR2-deficient mice with BMDM derived from the same mice to determine if alveolar macrophages differed in their response to chlamydia infection." (PMID 21695078, 2011). "Therefore, TLR2 signaling plays an important role in the early innate response caused by acute Chlamydia infection." (PMID 36607848, 2023). "This indicates that TLR2 agonists may be beneficial in the treatment of early life Chlamydia infections and associated diseases." (PMID 22724018, 2012). "TLR9—as already mentioned, most of the studies assessing host genetic determinants of Chlamydia infections are focusing on the extracellular TLR2's and TLR4's contribution to the differences in the susceptibility and severity of the infection." (PMID 23781508, 2013). "Vaccines are being developed to protect against Chlamydia infection, and recently TLR2 agonists have been used as effective adjuvants for anti-Chlamydia vaccines in mice." (PMID 22724018, 2012). "Collectively these results suggest that TLR2 is required to induce a protective Th1-mediated adaptive immune response in the lung in response to neonatal Chlamydia infection." (PMID 22724018, 2012). "While the immune mechanisms leading up to reproductive tissue damage in Chlamydia infections remain unclear, our findings highlight the involvement of mast cells in soluble mediator production, including IL-6, and suggest that TLR2 modulation may provide a mechanism to modify this cytokine response." (PMID 37138882, 2023). "In the current study, the response of human and mouse mast cells to Chlamydia infection was examined, and the impact of inhibiting the FPR and TLR2 pathways on key mast cell mediator responses was evaluated." (PMID 37138882, 2023). "Toll-like receptor 2 (TLR2) has been identified as an important receptor involved in the induction of IL-6, IL-8, granulocyte-macrophage colony-stimulating factor (GM-CSF), and TNF-α by epithelial cells or macrophages in response to Chlamydia infection." (PMID 32487756, 2020). "Since both innate and adaptive immunity contribute to the control of Chlamydia infection, we then investigated the impact of the absence of TLR2 on DCs that link innate and adaptive immune responses during the early stages of infection (3 and 7 dpi)." (PMID 22724018, 2012). "This interplay between TLRs 2 and 3 is representative of a possible regulation of TLR2-dependent immune responses by TLR3, and that this mechanism of regulation may be important to help control outcomes of Chlamydia infection in mice; particularly early- and mid-infection." (PMID 29624589, 2018). "Chlamydia infection resulted in increases in transcript levels of KC and MIP-2 to similar levels in the lungs of Wt and TLR2−/−, but not TLR4−/− or 2/4−/− mice, throughout the time course." (PMID 22724018, 2012).